CD24 (CD24 molecule)
Diseases named in the same sentence as CD24 in open-access papers (continued):
Sharing a sentence is not in itself a finding about the gene and the disease.
autoimmune disease (continued). "The important role of CD24 in the pathogenesis of autoimmune disease was initially investigated in animal models of experimental autoimmune encephalitis (EAE)." (PMID 36294907, 2022). "CD24 is a small, glycophosphatidylinositol-anchored cell surface protein, mostly investigated with respect to cancer, inflammation, and autoimmune diseases." (PMID 33562144, 2021). "The cell surface protein CD24 participates in various processes, including adaptive immune response, autoimmune disease, inflammation, and cancer." (PMID 32513298, 2020). "The opposing roles of CD24 expression in cancer and autoimmune diseases raise interesting questions on the role of sex differences in immunity underlying sex differences in cancer." (PMID 31615477, 2019). "Blocking CD24 through soluble CD24, consisting of the extracellular portion of murine CD24 and human IgG1 Fc ameliorated the clinical symptom of experimental autoimmune disease, the mouse model of multiple sclerosis." (PMID 27955675, 2016). "The protein CD24 has been reported to be involved in a diverse range of processes such as cancer, adaptive immunity, inflammation, and autoimmune diseases in other cell types." (PMID 26788063, 2016). "CD24 plays an important role in the adaptive immune response and controls an important genetic checkpoint for homeostasis and autoimmune diseases in both mice and humans." (PMID 26440795, 2015). "As CD5/CD1d are regulatory facrors in mouse models of inflammation and CD24/CD38 are involved in human autoimmune diseases, we assessed the expression of these markers in CD19+ B cells via flow cytometry." (PMID 26378021, 2015). "CD24 is widely distributed in hematopoietic and neuronal cells, many tissues, and some tumor stem cells, so it has been extensively used as a marker for adaptive immunity, inflammation, autoimmune diseases and cancers." (PMID 39953809, 2025). "While the role of CD24 in cancer has garnered significant attention, its importance extends to various other physiological and pathological processes, including autoimmune diseases, infectious disorders, Covid-19, neurological disorders, metabolic disorders and more." (PMID 38313430, 2023). "In addition to its functions in cancers, CD24 plays critical roles in autoimmune diseases, inflammation, and metabolic disorders." (PMID 36882399, 2023). "In the future, more studies and clinical trials may focus on the application of CD47-SIRPα and CD24-SIGLEC10 axes in autoimmune diseases." (PMID 37545490, 2023). "It is well acknowledged that inactivating CD24 might confer to protection against autoimmune diseases such as systemic lupus erythematosus and multiple sclerosis." (PMID 37359556, 2023). "CD24 is thought to be involved in various autoimmune diseases." (PMID 33562144, 2021). "CD24 may also be involved in adaptive immunity, inflammation, and autoimmune diseases and in the central nervous system (CNS)." (PMID 33562144, 2021). "While CD24 has not been associated with PD, polymorphisms in this gene does result in increased risk and progression of several autoimmune diseases, including multiple sclerosis, Crohn’s disease, and rheumatoid arthritis." (PMID 28182766, 2017). "While the function of CD24 in immune cells has been in focus in autoimmune diseases and RA, our studies provide the important insight that changes in CD24 expression in cartilage additionally modulate the cartilage response towards inflammation in cartilage degenerative diseases." (PMID 27955675, 2016). "Of particular note, CD24, although not detected in GWAS, is a gene that has been investigated thoroughly in regard to its association with autoimmune diseases, including MS, with promising results." (PMID 26039238, 2015). "The CD24 gene is crucial for the progression of autoimmune disease." (PMID 21651777, 2011).
autoimmune disease (continued). "CD24 on transitional B cells represents a central developmental stage in B-cell maturation, producing high levels of IL-10, which is considered to be related to chronic inflammatory and autoimmune diseases, including multiple sclerosis, rheumatoid arthritis, and systemic lupus erythematosus." (PMID 40612664, 2025). "While CD24 was first identified as a valuable marker for cellular development and differentiation, accumulating studies have revealed critical roles for CD24 in various pathological conditions, including autoimmune diseases, sepsis, metabolic disorders, graft vs host diseases and cancer." (PMID 37228622, 2023). "Studies using mouse models of autoimmune diseases have found that CD47-SIRPα and CD24-SIGLEC10 polymorphisms affect macrophages’ phagocytosis of apoptotic cells, suggesting that modulating the CD24-SIGLEC10 axis may have potential value in various musculoskeletal disorders." (PMID 37545490, 2023). "Although there are not yet many clinical trial reports on CD24-SIGLEC10-targeted therapies for autoimmune diseases, existing research provides a foundation for further exploration in this field." (PMID 37545490, 2023). "A decade ago, the initial connection between CD24 and autoimmune diseases surfaced when it was discovered that mice lacking CD24 displayed significant resistance to experimental autoimmune encephalomyelitis." (PMID 38313430, 2023). "Another question is whether CD24 blockage with the anti‐CD24 antibody leads to the over‐activation of TLR‐mediated pro‐inflammatory reactions, which in turn triggers a cytokine storm, attacks normal cells, and results in autoimmune diseases." (PMID 34363319, 2021). "Peripheral blood lymphocytes from 30 patients with DM, 37 patients with other autoimmune diseases (15 cases of SLE, 15 cases of RA and 7 cases of pSS), and 23 healthy individuals were phenotypically analyzed by flow cytometry for their expression of CD19, CD24, and CD38 surface markers." (PMID 27270362, 2016).
bladder cancer (32 papers, 2003 to 2025). "In bladder cancer, the increased expression of cytoplasmic CD24 is associated with the more aggressive progression of cancer and the recurrence of tumors." (PMID 39687458, 2024). "CD24 is highly expressed on bladder cancer samples, and it was associated with tumor cell proliferation, the potential of colony-forming units in soft agar cultures, and the regulation of apoptosis." (PMID 35628262, 2022). "A recent study shows that nuclear CD24 is associated with metastasis and poor outcomes in bladder cancer and CRC patients." (PMID 31614769, 2019). "This demonstrated that CD24 expression was significantly associated with the recurrence of bladder cancer." (PMID 23946784, 2013). "In addition, the incidence of bladder cancer induced by BBN was significantly lower in CD24-deficient male mice (29%) than in wild-type controls (45%) at 16 weeks." (PMID 32759680, 2020). "The results clearly indicated that higher CD24 protein expression may predict a higher risk of bladder cancer recurrence." (PMID 23946784, 2013). "The significant association of CD24 expression with the cancer grade and tumor recurrence rate suggests that CD24 induced a more malignant phenotype in the bladder cancer cells and that it may be involved in tumor recurrence by enhancing the attachment of tumors cells to the normal endothelium." (PMID 23946784, 2013). "CD24 is crucial in the advancement of bladder cancer metastasis, and the implementation of CD24 short hairpin RNA in bladder cancer cells leads to an almost complete termination of the tumour cells’ metastatic ability." (PMID 38137380, 2023). "Jason E Duex and colleagues have demonstrated that surCD24− cells in bladder cancer contain CD24 residues in the nucleoplasm, and that it is the nucleoplasmic CD24 (nucCD24) that is responsible for driving surCD24− growth and metastasis." (PMID 38137380, 2023). "A panel of CSC-related molecules were tested for their potential to detect bladder cancer, and the combination of CD24, CD49f, and NANOG showed promising sensitivity." (PMID 35565191, 2022). "The expression of bladder cancer stem-cell markers CD24 and CD44 was investigated on organoids as well." (PMID 35628262, 2022). "In contrast, a rather strong expression of CD24 was found at least in some areas of bladder cancer samples, but only a few cells expressed CD44 at barely noticeable levels, while CD276 positive cells were found in all samples." (PMID 35563359, 2022). "Bladder cancer stem cells have been described by expression of stem cell markers, among them CD24, CD44, and CD47, respectively." (PMID 35682984, 2022). "The increased expression of CD24 in metastatic tumors was identified in 60 paired primary and metastatic lesions of bladder cancer." (PMID 33260974, 2020). "Agreeing with previous studies showing that androgen/testosterone can activate CD24 expression in human bladder carcinoma cells, we also found that testosterone increased CD24 expression in our murine PCA models." (PMID 30467381, 2019). "CD24, a small cell surface protein, is expressed in different cancers such as breast, ovarian, prostate and bladder cancers." (PMID 31579438, 2019). "In animal models, CD24 overexpression and knockdown resulted in stimulation and inhibition, respectively, of the development of primary bladder cancer and its metastasis." (PMID 26770009, 2015). "Recently, CD24 has been described as a marker for bladder cancer metastasis formation and was shown to be required for metastasis to the lungs." (PMID 25247809, 2014). "The present study evaluated the CD24 expression in resected tumor specimens of bladder cancer and analyzed the correlation between this expression and the clinicopathological parameters." (PMID 23946784, 2013). "The present study is the first to show the potential involvement of CD24 in the development of more malignant bladder cancer and in the recurrence of tumors." (PMID 23946784, 2013).
bladder cancer (continued). "The expression and cellular distribution of the CD24 protein were determined by immunohistochemical staining in 125 paraffin-embedded bladder cancer tissues." (PMID 23946784, 2013). "It was previously shown that RalA depletion downregulated cell surface highly-glycosylated protein CD24 expression in bladder cancer cell lines." (PMID 21714887, 2011). "In bladder cancer cells, Ral GTPases, like Ras, influence the regulation of CD24." (PMID 38137380, 2023). "Moreover, CD24 was reported as a predictor of bladder cancer recurrence, and recent proof-of-principle studies provided promising results of anti-CD24 cancer therapy." (PMID 37626918, 2023). "Taken together, elevated expression of CD24 may serve as indicator for promising expansion of bladder cancer organoids." (PMID 35628262, 2022). "We conclude that elevated expression of CD24 on bladder cancer organoids may serve as an indicator for the in vitro culture and expansion capacities of BCOs." (PMID 35628262, 2022). "Furthermore, binding of AR to the CD24 promoter at an AR-responsive element in bladder cancer cells was suggested." (PMID 32759680, 2020). "CD24 expression and related activity have also been correlated with decreased tumor growth and metastasis in both xenograft and transgenic knockout mouse models of bladder cancer." (PMID 26862755, 2016). "AR signals activate CD24, a glycoprotein and a cell adhesion molecule, in bladder cancer cells." (PMID 26770009, 2015). "CD24 has recently been proposed as a drug target for anti-metastatic therapy in bladder cancer." (PMID 25247809, 2014). "Notably, the intensity of CD24 expression was also correlated with the intra-bladder tumor recurrence following treatment for bladder cancer." (PMID 23946784, 2013). "These insights may lead to future therapeutic strategies targeting CD24 to prevent the dissemination of bladder cancer cells and tumor recurrence." (PMID 23946784, 2013). "Its expression is increased in breast and bladder cancer metastasis compared to primaries and confers poor prognosis and CD24 knockdown abrogates metastasis in bladder cancer." (PMID 23982961, 2013). "CD24 expression may therefore be used not only as a prognostic marker in bladder cancer, but also as a target for the development of new therapeutic approaches, including antibody-based immunotherapeutic agents." (PMID 23946784, 2013). "Since the association between CD24 overexpression and bladder cancer recurrence has not been reported previously, the study was focused on the CD24 expression in cancer tissues and the intra-bladder tumor recurrence following transurethral surgical resection." (PMID 23946784, 2013). "CD24 has been shown to be RalA-regulated in a model of bladder cancer-derived cell lines." (PMID 21714887, 2011). "Moreover, experimental knock-down of CD24 expression in human bladder cancer cell lines reduced sphere formation, sensitivity to cisplatin-induced apoptosis, reduced the expression of the tumor stem-cell marker CD133, and attenuated tumor growth in an in vivo cancer model." (PMID 35628262, 2022). "We hypothesize that pathways regulating CD276—a bladder cancer cell and/or stem cell marker—are distinct and regulated independently from the other cancer stem cell markers investigated—i.e., CD24, CD44, and the ALDH1 paralog A1—and independent from the regulation of cell proliferation." (PMID 35563359, 2022). "Importantly, HIF–1α was revealed to induce CD24 mRNA expression by binding to the CD24 promoter in prostate and bladder cancer cells under hypoxia, identifying CD24 as a transcriptional target of HIF–1α and a critical downstream effector of HIF–1α–mediated survival and metastasis." (PMID 26444008, 2015). "However, the correlation of CD24 expression with bladder cancer and its prognostic significance remain largely unknown." (PMID 23946784, 2013).
bladder cancer (continued). "Others considered the expression of the aldehyde dehydrogenase (ALDH1) paralog A1, or the expression of CD24 and CD44 as bladder cancer stem cell markers." (PMID 35563359, 2022). "In this study, we explored the expression levels of CD276 and other bladder cancer stem cell markers including ALDH1, CD24, and CD44 as a function of cellular proliferation on UM-UC bladder cancer cells and NUCs." (PMID 35563359, 2022). "We therefore investigated the expression of CD276 as well as CD24 and CD44 in lymph node metastases of bladder cancer patients in comparison to bladder cancer samples." (PMID 35563359, 2022). "In addition, paraffin sections from bladder cancer tissue and metastases in lymph nodes were investigated for expression of CD276, CD24, and CD44." (PMID 35563359, 2022). "We conclude that not all bladder cancer tissue samples contained considerable numbers of CD24-positive cells." (PMID 35563359, 2022). "In the same study, striking increases in CD24 expression by androgen treatment were observed in AR-positive bladder cancer lines, although no such changes in non-neoplastic urothelial cells have been demonstrated." (PMID 32759680, 2020). "Immunohistochemical analyses in bladder cancer specimens have revealed that CD24 is expressed exclusively in tumor cells, but not in surrounding stromal cells." (PMID 26770009, 2015). "The 5-year overall recurrence-free rates of bladder cancer in the CD24-negative and -positive populations were 63.7 and 13.4%, respectively." (PMID 23946784, 2013). "The significant impact of CD24 knockdown in male mice on the rate of BBN-induced bladder cancer development was not seen in female mice (wild-type: 33% vs. CD24-deficient: 24% at 16 weeks), implying the involvement of AR signaling in CD24-mediated urothelial tumorigenesis." (PMID 32759680, 2020). "However, the lack of CD24 expression in all metastases and little expression of CD44 in bladder cancer tissues may reflect the wide variety of phenotypes found in malignant cells contributing to the cancer etiology." (PMID 35563359, 2022).
glioma (29 papers, 2003 to 2026). A benign or malignant brain and spinal cord tumor that arises from glial cells (astrocytes, oligodendrocytes, ependymal cells). "We identified nine risk immune cell phenotypes for glioma (such as CD19 on IgD( +) CD24(-)), and ten protective immune cell phenotypes (such as CD11c on monocytes)." (PMID 40343558, 2025). "Specifically, CD19 on IgD(+) CD24(−) B cells were identified as risk factors for glioma in this study." (PMID 40343558, 2025). "After binding to the CD24 promoter, a splice variant of Gli1 has been shown to upregulate CD24 and promote glioma invasion." (PMID 37919766, 2023). "Among these, 9 immune cell types, such as CD19 on IgD( +) CD24(−), were identified as risk factors for glioma, while 10 immune cell types, such as CD11c on monocyte, were considered protective factors for glioma." (PMID 40343558, 2025). "For instance, the association between memory B cells (CD27+ CD24+ B cells) and increased glioma risk aligns with recent studies suggesting that memory B cells may contribute to tumor progression by promoting an immunosuppressive microenvironment 50,53." (PMID 40657381, 2025). "Moreover, CD24 over-expression is associated with invasiveness in urothelial carcinoma and with migration and invasion in gliomas." (PMID 18433506, 2008). "For individuals identified as high-risk, such as those with elevated proportions of CD19 on IgD(+) CD24(−) B cells or abnormal levels of 7-hoca, early interventions like immunomodulators or metabolic interventions could potentially reduce the risk of glioma development." (PMID 40343558, 2025). "Intratumoral mitoxantrone administration in a murine CD24-high glioma model extended survival, decreased tumor size, reduced Siglec-10+/TREM2+ cell populations, and increased anti-tumor CD8+ cells." (PMID 41606146, 2026). "Conversely, CD24 significantly reduced the disease risk of COAD, lower grade glioma (LGG), and uterine carcinosarcoma (UCS)." (PMID 39791710, 2024). "CD24 showed substantially high expression levels in various cancers and cancer stem cells, such as breast cancer, pancreatic cancer, and glioma." (PMID 34363319, 2021). "In terms of B cells, we observed that CD27 on CD24+ CD27+ B cell and CD27 on unswitched memory B cell were positively correlated with glioma risk, suggesting that CD27 on B cell might play a role in tumor development." (PMID 40657381, 2025). "One of the possible mechanisms by which HPSE promotes glioma progression could be an induction of CD24 that provides glioma cell invasion, migration and proliferation and promotes tumor growth." (PMID 32075104, 2020). "CD24 expression was detected in 4 out of 6 low-grade gliomas." (PMID 18398462, 2008). "The expression of CD24 was observed in 7 of 16 high-grade gliomas analyzed." (PMID 18398462, 2008). "In contrast, the signal transducer and neural stem cell marker CD24 significantly correlates with a more favorable prognosis of glioma patients, and it has been suggested that it may be a marker that is specifically upregulated in IDH-mutated gliomas." (PMID 38275375, 2023). "This study elucidates Shikonin's capacity to effectively induce necroptosis in glioma cells, concurrently mitigating glioma stemness, as evidenced by diminished levels of stem cell markers, namely SOX2, CD44, CHI3L1, and CD24." (PMID 39619148, 2024). "To date, several CSC surface markers, including CD133, CD24, and CD44, have been reported in glioma." (PMID 37062068, 2023). "Conversely, LGR5− glioma cells showed low expression of CD133, CD44, CD90, CD24, and EpCAM, while the expression of CD90 remained unchanged in LGR5+ and LGR5− glioma cells." (PMID 30208924, 2018). "We found that LGR5+ glioma cells possessed considerably enhanced expression of CD133, CD44, CD90, CD24, and EpCAM." (PMID 30208924, 2018). "The expression levels of CD133, CD44, CD24, CD90 and EpCAM were examined in LGR5+ and LGR5− U251 and 8591 glioma cells by FCM." (PMID 30208924, 2018).